FREM2 (FRAS1 related extracellular matrix 2)
Description:
Extracellular matrix protein required for maintenance of the integrity of the skin epithelium and for maintenance of renal epithelia. Required for epidermal adhesion. Involved in the development of eyelids and the anterior segment of the eyeballs.
Synonyms: DKFZp686J0811; CRYPTOP; FRASRS2
Tractability: Antibody: UniProt places it where antibodies can reach, with high confidence; UniProt predicts a signal peptide or a membrane-spanning region; its Gene Ontology location is reachable by antibodies, with medium confidence.
Gene: Protein-coding gene on chromosome 13 (38,687,077 to 38,887,131, forward strand). Ensembl gene ENSG00000150893.
Subcellular location: Cell membrane
Subcellular location (Human Protein Atlas): Cytosol
Gene Ontology:
Molecular function: protein binding
Biological process: cell adhesion; eye development; cell-matrix adhesion; epithelial structure maintenance; cell communication
Cellular component: extracellular exosome; extracellular matrix; basement membrane; membrane; plasma membrane
Genetic constraint (gnomAD): Loss-of-function variants: 104 observed, 208.03 expected, observed/expected ratio (o/e) 0.5, 90% interval 0.43 to 0.59. The upper end of that interval is the gene's LOEUF score, 0.59, which puts it in group 2 of 6, group 1 being the genes least tolerant of losing a copy. Missense variants: 3,830 observed, 3,982.9 expected, observed/expected ratio (o/e) 0.96, 90% interval 0.94 to 0.99. Synonymous variants: 1,474 observed, 1,520.5 expected, observed/expected ratio (o/e) 0.97, 90% interval 0.93 to 1.01.
Homologues: Orthologues: chimpanzee FREM2 (99% identical), macaque FREM2 (98% identical), pig FREM2 (89% identical), guinea pig FREM2 (89% identical), rat Frem2 (88% identical), mouse Frem2 (88% identical), dog FREM2 (83% identical), rabbit FREM2 (82% identical), tropical clawed frog frem2 (71% identical), zebrafish frem2b (68% identical), zebrafish frem2a (66% identical). Paralogues in human: FREM3 (39% identical), FRAS1 (31% identical), FREM1 (22% identical), ADGRV1 (15% identical), SLC8A1 (7% identical), SLC8A2 (6% identical), SLC8A3 (6% identical).
Diseases named in the same sentence as FREM2 in open-access papers:
FREM2 is named in the same sentence as 51 diseases in open-access papers, as found by Europe PMC text mining. Sharing a sentence is not in itself a finding about the gene and the disease. The quoted sentences say what the papers report.
Fraser syndrome (20 papers, 2010 to 2025). Fraser syndrome is a rare clinical entity including as main characteristics cryptophthalmos and syndactyly. "This PPI network provides a foundation for further investigating the molecular mechanisms by which FREM2 variants lead to the phenotypic abnormalities observed in Fraser syndrome." (PMID 41426592, 2025). "The identification of two novel variants expands the FREM2 variant spectrum and also provides new insights into the genetic basis of Fraser syndrome 2, reinforcing the importance of high-throughput sequencing in uncovering the causes of rare genetic disorders." (PMID 41426592, 2025). "This article reports a case of Fraser syndrome 2 caused by compound heterozygous variants in the FREM2 gene, hoping to further enrich the understanding and research of this disease." (PMID 41426592, 2025). "We report a rare case of Fraser syndrome 2 caused by compound heterozygous mutations in the FREM2 gene." (PMID 41426592, 2025). "Regarding the PPI network, FREM2 interacts with several proteins known to be associated with Fraser syndrome, such as FRAS1, FREM1, and GRIP1." (PMID 41426592, 2025). "Fraser syndrome in humans results if any of the core members of the Fraser complex (Fras1, Frem1, Frem2) are mutated." (PMID 37047755, 2023). "In humans, FREM2 gene mutations can cause Fraser syndrome, a rare autosomal recessive genetic disease." (PMID 35252356, 2022). "In conclusion, we first reported two novel mutations in the FREM2 gene associated with the risk of Fraser syndrome." (PMID 34837691, 2021). "Two novel mutations c.7542_7543insG and c.2689C>T in the FREM2 gene were detected in this Fraser syndrome family by PCR-based sequencing." (PMID 34837691, 2021). "It was reported that homozygosity for a splice site mutation in the FREM2 gene was associated with Fraser syndrome and that compound heterozygosity for a missense mutation was related to cryptophthalmos." (PMID 32278351, 2020). "Mutations in Frem2 have been linked to Fraser's syndrome, which is a rare autosomal recessive disorder with a spectrum of malformations, including malformations of the ear." (PMID 28725177, 2017). "Of the candidate genes, four genes (i.e., ITGA8, GRIP1, FREM1, and FREM2) were Fraser syndrome-related genes, encoding proteins that functionally converged on the glial cell-derived neurotrophic factor/RET/bone morphogenic protein (BMP) signaling pathways." (PMID 29197384, 2017). "Genetic test revealed the typical mutations in the gene FREM2 confirming the diagnosis of Fraser Syndrome." (PMID 26552811, 2015). "Autozygosity mapping and candidate sequencing revealed that many Fraser syndrome cases are due to mutations in the genes encoding the proteins FRAS1 or FREM2, which belong to a family of large extracellular matrix proteins." (PMID 20419147, 2010). "Two of the disease genes underlying Fraser Syndrome in humans were identified as FRAS1 or FREM2, which encode structurally related basement membrane proteins." (PMID 20419147, 2010). "In this study, we report a fetus with Fraser syndrome 2 caused by two variants in the FREM2 gene." (PMID 41426592, 2025). "Therefore, in this case, the affected fetus is most likely suffering from Fraser syndrome 2 due to compound heterozygous variants that produce truncated proteins, disrupting the original structure of FREM2." (PMID 41426592, 2025). "However, we are convinced that the rare FREM2 variants found in our patients are associated with the supernumerary tooth phenotypes because it is well known that biallelic variants in FREM2 genes are associated with Fraser syndrome with dental anomalies." (PMID 37046432, 2023). "Fraser syndrome patients with FRAS1 or FREM2 variants share dental findings, including tooth agenesis and shortened roots, suggesting that the dental anomalies result from an impaired FRAS1-FREM2-FREM1 complex and subsequent abnormal epithelial–mesenchymal interactions." (PMID 37046432, 2023).
Fraser syndrome (continued). "Notably, the dental anomalies reported in biallelic patients with FREM2-associated Fraser syndrome were tooth agenesis and short roots." (PMID 37046432, 2023). "FREM2 itself is important for proper development of the eye and FREM2 mutation is associated with Fraser syndrome, in which cryptopthalamos (a congenital defect where the eyes are covered completely by skin and often associated with small or missing eyeballs) is commonly seen." (PMID 36603024, 2023). "A study of Fraser syndrome in a foetus found that mutations of FREM2 may lead to symptoms of double fingers and hidden eyeballs in foetuses with congenital high airway obstruction syndrome and renal hypoplasia after birth." (PMID 36195906, 2022). "Inherited mutations in FRAS1, and FREM2, have been associated with development of Fraser syndrome." (PMID 27047539, 2016). "Mutations in FRAS1 or FREM2 were found in approximately 50% of investigated cases of Fraser Syndrome, whereas the molecular lesions underlying the other half remain unknown." (PMID 20419147, 2010). "Biallelic variants in FREM2, FREM1, or FRAS1 result in Fraser syndrome (MIM 607830; 608945; 604597), a rare autosomal recessive malformation syndrome characterized by cryptophthalmos, syndactyly, urogenital abnormalities, and dental anomalies." (PMID 37046432, 2023). "Genetic test revealed the mutations c.[5752dup];[8544+1G>T] p.[(Cy51918fs)], in the gene FREM2 confirming the diagnosis of Fraser Syndrome." (PMID 26552811, 2015). "For example, mutations in the zebrafish orthologues of human FRAS1, FREM1 and FREM2 recapitulate the epidermal blistering of distal appendages seen in Fraser Syndrome." (PMID 24400120, 2014). "As mentioned, truncated proteins caused by premature stop codons are generally considered to lose biological function, and such structural abnormalities in FREM2 likely impair its ability to perform normal cellular roles, which is a key factor in the development of Fraser syndrome 2 in the fetus." (PMID 41426592, 2025). "Carriers of FREM2 heterozygous variants including the heterozygous parents of patients with FRASER syndrome have not been reported to have dental anomalies." (PMID 37046432, 2023). "Therefore, we encourage clinical and radiographic evaluations of parents of children with FREM2-related Fraser syndrome for dental anomalies, which would further prove the pathogenicity." (PMID 37046432, 2023). "Biallelic variants in FREM2 are implicated in Fraser syndrome, and heterozygous carriers of the FREM2 variants have not been reported to have phenotypes." (PMID 37046432, 2023). "The phenotypes of Fraser syndrome caused by variants in FREM2, FREM1, or FRAS1 are not distinguishable." (PMID 37046432, 2023). "However, in one large literature review, abnormal lung lobulation was documented in 5/117 (4.3%) of cases of Fraser syndrome, which can be caused by recessive mutations in FRAS1, FREM2 and GRIP1." (PMID 23536828, 2013). "Recessive mutations in FRAS1, FREM2, and GRIP1 cause Fraser syndrome which is characterized by cognitive impairments, cryptophthalmos, syndactyly, genital and renal anomalies and a range of other structural defects including CDH, lung lobulation defects and anal anomalies (OMIM #219000)." (PMID 23536828, 2013).
glioblastoma (9 papers, 2018 to 2025). The most malignant astrocytic tumor (WHO grade IV). "NB3F18, as we named it, is directed against the membrane-associated protein FREM2, overexpressed in glioblastoma stem cells." (PMID 39982223, 2025). "FREM2 appeared a relatively weak diagnostic biomarker as it showed low or statistically unreliable AUC values for almost all pairwise comparisons except “glioblastoma, IDH-wildtype” vs “oligodendroglioma, IDH-mutant, and 1p/19q-codeleted”." (PMID 36613601, 2022). "FREM2 was positively associated with survival in glioblastoma IDH-WT and negatively associated in low grade glioma IDH-WT (all associations were significant, p < 0.05)." (PMID 31357584, 2019). "The authors of this study performed whole exome deep sequencing of in-vitro temozolomide-treated residual cell cultures, and reported a 76% variant allele frequency enrichment of FREM2 in their aggressive glioblastoma-derived neurospheres." (PMID 31357584, 2019). "Due to the membrane-associated localization of FREM2 and its overexpression in glioblastomas, the FREM2-specific nanobody can be used for selective targeting of glioblastoma cells with minimal damage to adjacent cells and without the need for entering the cell." (PMID 39982223, 2025). "In addition, it has been suggested that FREM2 has a role in glioblastoma pathology and is associated with favorable patient prognosis." (PMID 31357584, 2019). "Finally, these data show that increased FREM2 gene expression is associated with favorable prognosis for patients with IDH-WT glioblastomas." (PMID 31357584, 2019). "It is now a challenge for the research community to determine whether the FREM2 changes detected are a cause for or a consequence of glioblastoma formation." (PMID 31357584, 2019). "In addition, variant allele frequency enrichment of FREM2 in temozolomide-resistant glioblastoma cells has been reported previously." (PMID 31357584, 2019). "The nanobody characterized in this study can be used as a robust molecular tool to analyze the role of FREM2 in glioblastoma initiation and progression in vitro and potentially in vivo." (PMID 39982223, 2025). "In our previous research we identified and validated the FRAS1-related extracellular matrix 2 (FREM2) gene and protein as a specific component of glioblastomas in silico, in vitro, and in human tissue samples." (PMID 39982223, 2025). "As supported by our STRING analysis, FREM2 plays a crucial role in regulating the differentiation and migration of glioblastoma stem cells through ECM and integrins." (PMID 39982223, 2025). "At last, the high FREM2 expression in glioblastoma cohorts strengthens the potential use of FREM2 as a therapeutic target." (PMID 39982223, 2025). "In our previously published research, FREM2 was found to be specific for glioblastoma cells, i.e., overexpressed in GSCs compared to differentiated glioblastoma cells at the gene and protein levels." (PMID 39982223, 2025). "To examine the cellular localization of FREM2 in glioblastoma cells and astrocytes, we performed live cell imaging that allows for incubation of NB3F18-546Alexa with the cells while they were still in a metabolically active state." (PMID 39982223, 2025). "Data obtained from our experiments suggested that NB3F18 can be used as a molecular tool to study and uncover the role of FREM2 in glioblastoma pathogenesis." (PMID 39982223, 2025). "We found that FREM2 pathway was a superior biomarker to the FREM2 gene expression level itself to discriminate glioblastomas and lower grade gliomas and to predict survival within different glioma subgroups." (PMID 36613601, 2022). "Lower FREM2 expression and overexpression of CRNDE (Colorectal Neoplasia Differentially Expressed) non-coding RNA are associated with worse prognosis for glioblastoma patients." (PMID 36613601, 2022). "We demonstrate increased FREM2 protein expression levels in glioblastomas compared to reference samples." (PMID 31357584, 2019).
glioblastoma (continued). "We conclude that FREM2 has an important role in malignant progression of glioblastoma, and we suggest deeper analysis to determine its involvement in glioblastoma pathology." (PMID 31357584, 2019). "Due to the observed changes at both the proteomic and transcriptomic levels, we therefore suggest further exploration of FREM2 in both primary and recurrent glioblastomas, to evaluate its role in disease progression." (PMID 31357584, 2019). "Multivariate analysis showed positive association between FREM2 and favorable prognosis of IDH-wild type glioblastoma." (PMID 31357584, 2019). "The results of this study suggest the involvement of the FREM2 gene and its protein in glioblastoma pathogenesis, and they will serve as the basis for further evaluation of their roles in glioblastoma progression." (PMID 31357584, 2019). "The observed cytotoxicity in glioblastoma stem cells may be due to the functional modulation of FREM2 by NB3F18." (PMID 39982223, 2025). "Upregulated FREM2 protein expression was demonstrated in glioblastomas compared to normal samples." (PMID 35620462, 2022). "Recently the role of the FREM2 gene has been shown in glioblastoma progression." (PMID 34439271, 2021). "On that account, because it was found robust, comparable to IDH mutation status, and superior to MGMT methylation status in most of the comparisons, we propose FREM2 pathway activation as a novel robust predictor of unfavorable prognosis of glioblastoma patients." (PMID 34439271, 2021). "Recently we showed that the FREM2 gene has a role in glioblastoma progression." (PMID 34439271, 2021). "On the other hand, our findings clearly show differential expression of the FREM2 protein in glioblastoma tissue samples, which might be relevant for further use in clinical practice." (PMID 31357584, 2019). "Moreover, multivariate analysis showed that FREM2 gene expression is positively correlated with patient overall survival in glioblastoma and negatively correlated in IDH-WT low grade glioma." (PMID 31357584, 2019). "Due to its membrane association, and considering its overexpression is related to tumor grade and progression, FREM2 might be an attractive target for glioblastoma cell targeting." (PMID 31357584, 2019). "In the present study we used instead patient samples to confirm this involvement of the FREM2 gene and its protein in glioblastoma pathology as the malignancy progresses, as shown by the higher FREM2 expression levels in glioblastoma tissues compared to lower grade gliomas and reference samples." (PMID 31357584, 2019). "The involvement of FREM2 in glioblastoma progression might also be correlated to the presence of hypermutation, which can commonly occur as a result of chemotherapy treatment." (PMID 31357584, 2019). "Our experimental data also suggest the involvement of FREM2 in glioblastoma pathogenesis." (PMID 31357584, 2019). "In addition, FREM2 was overexpressed in glioblastoma stem-like cells in comparison to mature GBM cells as well as neural stem cells which highlights this protein as a putative biomarker of glioblastoma stem cells." (PMID 29734672, 2018). "In conclusion, we identified two new cell-surface glioblastoma marker candidates, FREM2 and SPRY1." (PMID 29734672, 2018). "FREM2 is thus proposed as a novel GB biomarker and a putative biomarker of glioblastoma stem cells." (PMID 29734672, 2018). "In addition, FREM2 gene and protein expression levels are higher in GB stem-like cell lines than in conventional glioblastoma cell lines." (PMID 29734672, 2018). "Moreover, qRT-PCR results proved significantly elevated expression of FREM2 in glioblastoma stem-like cells when compared to mature GBM cells." (PMID 29734672, 2018). "In particular, it had been previously shown that high expression of genes FREM2 (FRAS1 Related Extracellular Matrix 2) and SPRY1 (Sprouty RTK Signaling Antagonist 1) is specific to glioblastomas." (PMID 36613601, 2022).